SPP1 (secreted phosphoprotein 1)
Diseases named in the same sentence as SPP1 in open-access papers (continued):
Sharing a sentence is not in itself a finding about the gene and the disease.
glioma (continued). "The present study investigated the functional roles of SPP1 and HMOX1 in glioma and explored the downstream regulatory mechanism modulated by SPP1 and HMOX1." (PMID 40495644, 2025). "The current study is the first to demonstrate that SPP1 and HMOX1 downregulation in glioma cells infected with VSV‐M51 reveals a potential mechanism whereby VSV‐M51 infection modulates glioma." (PMID 40495644, 2025). "GSEA analysis revealed the activation of cancer cell proliferation, EMT and tumour metastasis in the SPP1/HMOX1 overexpression group compared to the control group, indicating potential regulatory roles in glioma progression." (PMID 40495644, 2025). "Our results emphasised the importance of SPP1 and HMOX1 as novel targets for oncolytic virotherapy intervention, holding promise for glioma treatment." (PMID 40495644, 2025). "An interaction between SPP1 and CD44 has previously been postulated for glioma, yet here we show an unexplored role of these molecules in conveying communication between GTCs, microglial cells and T cells." (PMID 39880824, 2025). "This study also examined the roles of SPP1 and HMOX1, alongside the in‐depth regulatory mechanisms in glioma." (PMID 40495644, 2025). "Each one of the two correlation coefficients manifested that both SPP1 and HMOX1 were consistently co‐expressed with 20 genes in glioma samples, such as VAMP8, RAC2, MSR1, CAPG and FBP1." (PMID 40495644, 2025). "One key signaling axis involves SPP1 (osteopontin) and CD44, which facilitates glioma cell migration and invasion and is largely mediated by TAM-derived factors." (PMID 41272822, 2025). "For TUBA1B-high-expressing Glioma cells, signal output was primarily through the PTN, ANNEXIN, VEGF, PROS, and BMP pathways, while signal input occurred via the PTN, SPP1, and MK pathways." (PMID 40094001, 2025). "qPCR and HPA analysis were utilised to assess the mRNA/protein levels of SPP1 and HMOX1 in glioma tissues." (PMID 40495644, 2025). "The GSE166914 dataset was analysed to examine the SPP1 and HMOX1 expression after VSV‐M51 infection in glioma." (PMID 40495644, 2025). "The significant elevated expression of SPP1 and HMOX1 was detected in the samples diagnosed with classified as WHO G4/G3 gliomas in comparison to those with G2 glioma tissues (p < 0.001)." (PMID 40495644, 2025). "The data revealed that high SPP1/HMOX1 expression is positively related to patient age, IDH WT status, 1p/19q codeletion, and primary treatment outcome, suggesting that SPP1 and HMOX1 play crucial roles in the progression of glioma (p < 0.001)." (PMID 40495644, 2025). "Our study proposed, for the first time, that SPP1/HMOX1 contributeso the activation of the PI3K/AKT, JAK–STAT and syndecan 1 signalling pathways, thereby maintaining the motility and malignancy of glioma cells." (PMID 40495644, 2025). "As a result, patients with high level of both SPP1 and CD44 had an increased macrophages infiltration and a poor prognosis in glioma." (PMID 38346944, 2024). "In gliomas, SMOC1, S100A6, CTSB, SPP1, and IGFBP2 serve as a potential therapeutic target in glioma." (PMID 39530009, 2024). "A previous scRNA-seq analysis revealed SPP1/CD44-mediated crosstalk between macrophages and cancer cells in glioma." (PMID 36776876, 2023). "PLOD2, Spp1, SPOCK1 and CRLF1 can also serve as new targets for anti-tumor microenvironment therapy of glioma." (PMID 36819132, 2023). "A recent single‐cell study of glioma also revealed that SPP1/CD44‐mediated intercellular interaction between macrophages and cancer cells plays a critical role in glioma progression." (PMID 37194413, 2023). "A recent comparative RNA-seq analysis identified that many genes are commonly upregulated in both gliomas (eg., IDH wild-type) and BrMs, including the angiogenic factor VEGFA, growth factors PDGFA, TGFB1, SPP1, and the protease inhibitor TIMP-116." (PMID 36216799, 2022).
glioma (continued). "SPP1 was also recognized as a ligand for CD44, and SPP1-CD44 communication augmented the stemness of CD44 secretory glioma-stimulatory cells." (PMID 35419058, 2022). "Altogether, this study revealed a critical role of macrophage-mediated SPP1/CD44 signaling in high-grade glioma, providing a new therapeutic target for the precision treatment of glioma." (PMID 34805184, 2021). "Some intriguing aspects of the core gene set identified in this study include the well-studied glioma-related genes ANGPT2, CD44, SPP1, STAT3, PDGRFA, and TOP2A (all up-regulated), and BRSK1, DKK3, FGFR2, MAPK9, MEF2C, and PTEN (all down-regulated)." (PMID 29352201, 2018). "The transcriptional regulation of the SPP1 expression by GLI1 (and likely OCT4) in glioma cells resembles the stem cell-type regulation." (PMID 28030801, 2017). "Deletion analyses of the SPP1 gene promoter and gel shift studies demonstrated c-Myc and OCT-1 binding to the proximal promoter of SPP1 gene in U251MG and U87MG human glioma cells." (PMID 28030801, 2017). "We demonstrate overexpression of two out of five SPP1 isoforms in glioblastoma (GBM) and differential isoform expression in glioma cell lines." (PMID 28030801, 2017). "Our observation is consistent with recently reported data demonstrating that stably knockdown of SPP1 in U87MG and GBM4371 glioma cells reduced their sphere forming capacity." (PMID 28030801, 2017). "Glioma-myeloid and myeloid-glioma signaling identified EGFR, SPP1, MIF, and other important LRI." (PMID 40191211, 2025). "Moreover, our data reveal that elevated levels of SPP1/HMOX1 are observed across different glioma histological types, with higher expression noted in high‐grade glioma patients compared to those with low‐grade glioma." (PMID 40495644, 2025). "Furthermore, immunohistochemical analysis showed that SPP1 and HMOX1 were significantly upregulated in glioma tissues compared to cerebral cortex tissues." (PMID 40495644, 2025). "To evaluate the potential role of SPP1/HMOX1 in promoting tumour progression in glioma, we examined whether silencing SPP1 and HMOX1 affects glioma cell viability and apoptosis." (PMID 40495644, 2025). "SPP1 and HMOX1 have the potential to be biomarkers for the diagnosis and prognosis of glioma." (PMID 40495644, 2025). "Despite evidence showing SPP1+TAM promoting glioma cell survival by secreting SPP1 or interacting with tumor cells, it is unclear how this population is regulated or how it affects T cell function in gliomas." (PMID 38515213, 2024). "We then performed clustering on the TAM subsets from the 17 cross-grade glioma patients and found three major TAM subsets with distinguished expression of CCL3, AIF1, and SPP1 respectively, the three subsets also share most of the marker genes with the previously identified TAMs in grade 2 glioma." (PMID 38515213, 2024). "Moreover, monitoring the composition of TAMs, especially SPP1+TAM, in low-grade gliomas is important for prognosis prediction." (PMID 38515213, 2024). "Additionally, it had been demonstrated that SPP1/CD44 interaction mediated crosstalk between macrophages and glioma cells." (PMID 38346944, 2024). "Western blot showed that probiotic combination suppressed N-cadherin protein expression (p < 0.05), but did not statistically affect the protein expression of Spp1 in glioma tissues." (PMID 36147842, 2022). "This strategy has been related to the overexpression of Spp1 (secreted phosphoprotein 1 or osteopontin) and Mgfe8 (milk fat globule-EGF factor 8 or lactadherin) on glioma cells and human glioblastoma tissue, which prompt M2 reprogramming of MG as a result of integrin signaling activation." (PMID 34168976, 2021). "Moreover, we showed that there is a strongly positive correlation between SPP1 and CD68 expression levels in glioma samples, Similarly, positive correlation between VIM and CD68 expression levels in glioma samples was observed." (PMID 34805184, 2021).
glioma (continued). "Notably, the SPP1/CD44 signaling in the perivascular niche has been shown to promote the stem cell-like properties and radiation resistance of glioma cells." (PMID 34805184, 2021). "Finally, we showed that high expression levels of both SPP1 and CD44 correlate with an increased infiltration of macrophages and poor prognosis of glioma patients." (PMID 34805184, 2021). "Finally, we investigated the clinical significance of increased expression of SPP1 and CD44 in glioma." (PMID 34805184, 2021). "Our data show a novel transcriptional mechanism driving SPP1 expression in glioma cells that is not in operation in non-transformed astrocytes." (PMID 28030801, 2017). "The levels of Spp1, Nanog and Oct3/4 mRNAs were augmented in the Rhod123(–) cells isolated from the rat C6 glioma cultures when compared with their expression in non-transformed astrocytes." (PMID 28030801, 2017). "We demonstrated that transcription factors OCT4 and GLI1, involved in maintenance of the stemness phenotype in embryonic and cancer stem cells, bind to the SPP1 gene in glioma cells, but not in normal astrocytes." (PMID 28030801, 2017). "In addition, SPP1-mediated signaling through Akt and ERK is suggested to affect migration in glioma cells by activation of NRF2, which would suggest a positive feedback loop." (PMID 27562236, 2017). "To determine whether SPP1 is overexpressed in GIC, we measured SPP1 mRNA levels in adherent and 3-D, sphere cultures developed from human and rat glioma cells." (PMID 28030801, 2017). "Glioma cells depleted of the endogenous Spp1 and overexpressing a neutral plasmid pEGFP failed to form spheres." (PMID 28030801, 2017). "Using chromatin immunoprecipitation we found binding of the OCT4 protein to the first intron of the SPP1 gene in human glioma cells, but not in NHA." (PMID 28030801, 2017). "Knockdown of Spp1 in glioma cells did not affect basal cell viability and proliferation determined with MTT metabolism and BrdU incorporation test." (PMID 28030801, 2017). "Up-regulated SPP1 expression is associated with binding of the GLI1 transcription factor to the promoter and OCT4 (octamer-binding transcription factor 4) to the first SPP1 intron of the SPP1 gene in human glioma cells but not in non-transformed astrocytes." (PMID 28030801, 2017). "Notably, SPP1/HMOX1 and co‐expressed genes were related to activating the PI3K/AKT, JAK–STAT and syndecan 1 pathways in glioma, contributing to the tumour progression of glioma." (PMID 40495644, 2025). "Moreover, our data suggested that blocking SPP1 and PTN pathways might be a strategy for combating glioma." (PMID 36036011, 2022). "Here we present GPNMB and SPP1 as possible new targets and could show that these genes are highly expressed in GAMs in different glioma mouse models, in human GBM, and that high expression of these genes is correlated with shorter glioma-patient survival." (PMID 25658639, 2015). "Limitations of the current study include the lack of data regarding the regulatory mechanism of SPP1 and/or HMOX1 in glioma cell growth, as well as not providing in‐depth profiling for SPP1 and/or HMOX1 in different histologic grades of LGG or GBM." (PMID 40495644, 2025). "We demonstrated binding of GLI1 to the proximal promoter of SPP1 gene by chromatin immunoprecipitation (ChIP) assay in three human glioma cell lines, including primary human WG4 glioma cultures, but not in NHA." (PMID 28030801, 2017). "However, the roles of SPP1 and HMOX1 in glioma are not yet understood and require further exploration." (PMID 40495644, 2025). "Due to its very low level in glioma cells, we could not demonstrate the efficacy of OCT4 silencing (not shown) and prove its role in the transcriptional SPP1 regulation." (PMID 28030801, 2017).
glioma (continued). "Here we found that the SPP1 gene mainly expresses in the macrophages rather than tumor cells, whereas the CD44 primarily expresses in the MES-like cells, suggesting that TAM-secreted OPN may regulate the mesenchymal phenotype of glioma by interacting with CD44 on tumor cells." (PMID 34805184, 2021).
prostate carcinoma (117 papers, 2006 to 2026). A carcinoma that arises from epithelial cells of the prostate gland. "Chandran identified SPP1 as a gene linked to prostate cancer metastasis through gene expression profiling." (PMID 41391064, 2025). "As a result, AR, TREM2, and APOE are overexpressed in prostate cancer and correlate with poor prognosis The role of SPP1-expressing TAMs in tumor progression is under active investigation, and high SPP1 expression is linked to an unfavorable prognosis." (PMID 41417432, 2025). "SPP1 is crucial for prognosis in prostate cancer, with high expression levels linked to worse clinical outcomes." (PMID 41391064, 2025). "One notable investigation pinpointed ‘lipid-loaded’ tumor-associated macrophages, marked by high Spp1 expression, that bore a direct correlation with prostate cancer progression." (PMID 38001899, 2023). "In various cancer types, including lung, breast, colon, and prostate cancer, overexpression of SPP1 is associated with tumor invasion, metastasis, and poor clinical outcome." (PMID 35565305, 2022). "Next, PCa cell lines with overexpression or depletion of SPP1 were established to study the effect of SPP1 on enzalutamide sensitivity and adhesion and migration of prostate cancer cell lines and further explore the underlying regulatory mechanisms." (PMID 34721759, 2021). "We observed a clear amplification pattern in prostate cancer, whereas mutations in SPP1 primarily occurred in cutaneous melanoma and endometrial cancer." (PMID 31849319, 2019). "Here we use single-cell profiling on patient biopsies across the disease continuum and find that a distinct population of tumour-associated macrophages with elevated levels of SPP1 transcripts (SPP1hi-TAMs) becomes enriched with the progression of prostate cancer to mCRPC." (PMID 39633050, 2025). "Recent studies have reported that SPP1 is significantly associated with cell growth, adherence and invasion in tumourigenesis and metastasis, and is over-expressed in lung, colon, breast, and prostate cancers." (PMID 31849319, 2019). "Interestingly, we found that both the LEPR Gln223Arg homozygous A and SPP1-66 homozygous G were significantly associated with all outcomes (risks of overall, high-grade, and high metastatic-risk prostate cancers)." (PMID 22792137, 2012). "Using 3D cultures and in vivo experiments, it was shown that macrophage-derived SPP1 speeds up the transition from PIN to prostate cancer." (PMID 41391064, 2025). "For instance, eIF4E-driven selective translation of Hgf, Spp1 and Bgn suppresses immunotherapy by recruiting MDSCs in prostate cancer, while eIF2α phosphorylation-mediated integrated stress response (ISR) underlies sorafenib resistance of HCC." (PMID 41144132, 2025). "DEU patterns were much more noticeable as compared to breast and prostate cancer, with SPP1 as well as its interacting partners S100A4 and CXCL12 showing significant differences in exon usage in tumor-affected samples." (PMID 39857756, 2025). "Single-cell profiling of human prostate cancer and studies in mouse models show that macrophages expressing SPP1 mediate immunotherapeutic resistance through adenosine pathway activation and represent a potential target for future studies." (PMID 39633050, 2025). "SPP1 knockdown enhanced enzalutamide sensitivity and repressed invasion and migration of prostate cancer cells." (PMID 34721759, 2021). "SPP1 participates in the recurrence and metastasis of prostate cancer by mediating the BP of the Smad4/PTEN pathway." (PMID 33954053, 2021). "According to OPN status in prostate cancer as a bad prognosis marker, SPP1 expression has been found overexpressed between non-tumoral, primary site and metastasis localization." (PMID 33284790, 2020). "SPP1 is an integrin-binding glyco-phosphoprotein, which shows over-expression in a variety of tumors, such as liver cancer, LC, prostate cancer (PCa), BC, and CRC." (PMID 33324676, 2020).
prostate carcinoma (continued). "SMAD4 is a key regulator of the TGFβ pathway and a suppressor of prostate tumor progression, whereas cyclin D1 and SPP1 act as mediators of the prostate cancer processes." (PMID 31551414, 2019). "Using this approach, we confirm that four previously reported prognostic markers, PTEN, SMAD4, CCND1 and SPP1, can predict lethal outcome of human prostate cancer." (PMID 25075204, 2014). "In the prostate cancer group with high risk for metastasis, only the LEPR Gln223Arg, SPP1-66 T>G and FGF2+223 C>T genetic variants, age and PSA persisted." (PMID 22792137, 2012). "In prostate cancer, elevated plasma SPP1 levels have been correlated with bone metastasis and poorer survival." (PMID 21152079, 2010). "A study demonstrated that a class of tumor-associated macrophages (SPP1 hi-TAMs), which highly express SPP1 and secrete adenosine to activate the A2AR signaling pathway, emerged in metastatic desmoplasia-resistant prostate cancer, leading to ICIs resistance in vivo." (PMID 41200193, 2025). "Recently, SPP1 has been identified as one of the autophagy-related genes and the autophagy-related gene signature can predict clinical outcomes and therapy response in prostate cancer." (PMID 38466483, 2024). "SPP1 is involved in the tumor microenvironment of pancreatic and prostate cancer." (PMID 36769187, 2023). "In addition, SPP1 predicted prostate cancer risks in urine sediments better than previously reported biomarkers." (PMID 37696527, 2023). "Recent researches demonstrated that overexpressing of SPP1 could be used as an indicator of poor prognosis in numerous human cancers, for instance, lung cancer, gastric carcinoma, colorectal cancer, and prostate cancers." (PMID 35067176, 2022). "All four could regulate the expression of collagen or SPP1, thereby exerting regulatory effects on the invasion and metastasis of prostate cancer cells." (PMID 36389722, 2022). "Besides, Toshihisa el al. also reported Runx2 plays an important role in the bone metastasis of breast and prostate cancers by up-regulating SPP1." (PMID 33365318, 2020). "Recent study reported that SPP1 can increase CD44 expression in prostate cancer cells." (PMID 33324676, 2020). "Inactivation of PTEN and SMAD4 and activation of cyclin D1 and SPP1 promote prostate cancer." (PMID 31551414, 2019). "However, there are rare studies of OPN mediated drug resistance of prostate cancer, and the role of SPP1 in mCRPC is still elucidated." (PMID 31620371, 2019). "Interestingly, the interaction between CD44 and Mmp9 in PC3 prostate cancer cells has been demonstrated to be induced by Spp1." (PMID 24304664, 2013). "The SNPs in LEPR Gln223Arg, SPP1-66 T>G, IGF1R+3174 G>A, IGFBP3-202 A>C, FGF2+223 C>T and IL6-597 G>A, plus age and PSA remained independently associated with risk for overall, and for high-grade prostate cancer." (PMID 22792137, 2012). "Further detailed studies are required to address the specific role of SPP1 and other co-expressed genes in prostate cancer metastasis and whether SPP1 represents a potential therapeutic target for androgen-resistant disease." (PMID 17430594, 2007). "Similarly, the role of SPP1 in prostate cancer has been confirmed in several other studies." (PMID 41293726, 2025). "In prostate cancer, FAP+ stromal programmes co‐occur with immunosuppressive myeloid states (e.g., CD163+/SPP1+ macrophages) and FAP itself can also promote macrophage activation and tissue remodelling." (PMID 41410015, 2026). "In prostate cancer models, PARPi-conditioned media drive chemotaxis of CCR2 positive monocytes and SPP1- or TREM2-biased TAM polarization during exposure to hypoxic and lipid-rich microenvironments, characteristics of the bone metastatic microenvironment." (PMID 41488638, 2025).